STYX (serine/threonine/tyrosine interacting protein)
Description:
Catalytically inactive phosphatase. Acts as a nuclear anchor for MAPK1/MAPK3 (ERK1/ERK2). Modulates cell-fate decisions and cell migration by spatiotemporal regulation of MAPK1/MAPK3 (ERK1/ERK2). By binding to the F-box of FBXW7, prevents the assembly of FBXW7 into the SCF E3 ubiquitin-protein ligase complex, and thereby inhibits degradation of its substrates. Plays a role in spermatogenesis (By similarity).
Tractability: PROTAC: ubiquitination databases record sites on it.
Gene: Protein-coding gene on chromosome 14 (52,730,043 to 52,774,989, forward strand). Ensembl gene ENSG00000198252.
Subcellular location: Nucleus; Cytoplasm, cytosol
Subcellular location (Human Protein Atlas): Nucleoplasm
Gene Ontology:
Molecular function: F-box domain binding; protein binding; pseudophosphatase activity
Biological process: negative regulation of protein binding; negative regulation of SCF-dependent proteasomal ubiquitin-dependent catabolic process; regulation of ERK1 and ERK2 cascade
Cellular component: cytoplasm; nucleus; cytosol
Genetic constraint (gnomAD): Loss-of-function variants: 13 observed, 25.97 expected, observed/expected ratio (o/e) 0.5, 90% interval 0.32 to 0.8. The upper end of that interval is the gene's LOEUF score, 0.8, which puts it in group 3 of 6, group 1 being the genes least tolerant of losing a copy. Missense variants: 143 observed, 162.35 expected, observed/expected ratio (o/e) 0.88, 90% interval 0.77 to 1.01. Synonymous variants: 43 observed, 51.13 expected, observed/expected ratio (o/e) 0.84, 90% interval 0.66 to 1.08.
Homologues: Orthologues: chimpanzee STYX (100% identical), guinea pig STYX (98% identical), macaque STYX (98% identical), dog STYX (96% identical), mouse Styx (96% identical), mouse Styx-ps (96% identical), pig STYX (91% identical), rabbit STYX (90% identical), tropical clawed frog styx (85% identical), zebrafish styx (78% identical), Caenorhabditis elegans Y54F10BM.13 (32% identical). Paralogues in human: DUSP16 (30% identical), DUSP8 (30% identical), DUSP1 (28% identical), SSH1 (27% identical), SSH2 (27% identical), DUSP19 (26% identical), DUSP2 (26% identical), DUSP4 (26% identical), DUSP9 (26% identical), SSH3 (26% identical), DUSP10 (25% identical), DUSP6 (25% identical), and 19 more.
Diseases named in the same sentence as STYX in open-access papers:
STYX is named in the same sentence as 10 diseases in open-access papers, as found by Europe PMC text mining. Sharing a sentence is not in itself a finding about the gene and the disease. The quoted sentences say what the papers report.
breast carcinoma (4 papers, 2019 to 2021). "Furthermore, the expression of STYX and FBP is implicated in breast cancer patients, where patients’ survival is modulated by the disruption of the balance between STYX and FBXW7 expression." (PMID 34203203, 2021). "In breast cancer cells, STYX has been found to suppress FBXW7 expression through direct protein‐protein binding." (PMID 33822486, 2021). "A majority of study testified STYX acts as a latent oncogene, suggesting that STYX restrained cell apoptosis in colorectal and breast cancer by binding F-box and WD40 domain protein 7 (FBXW7, also called hCDC4, Fbw7) protein." (PMID 32239181, 2020). "A proof demonstrated that STYX suppresses FBXW7 expression via direct protein–protein interaction in breast cancer cells." (PMID 32239181, 2020). "STYX has been associated with cell proliferation, migration, invasion, and apoptosis in colorectal cancer cells and a range of studies have indicated that STYX acts as a latent oncogene that inhibits apoptosis in colorectal and breast cancer, mainly by binding to FBXW7." (PMID 33822486, 2021). "In addition, STYX regulates apoptosis in breast cancer cells and HeLa cells through cross-talk with FBXW7." (PMID 31608184, 2019).
colorectal cancer (3 papers, 2020 to 2021). A primary or metastatic malignant neoplasm that affects the colon or rectum. "Because these proteins support epithelial to mesenchymal transition, STYX may promote the oncogenesis of colorectal cancer by positively regulating the epithelial to mesenchymal transition." (PMID 34203203, 2021). "In addition, STYX promotes oncogenesis in colorectal cancer by inhibiting FBXW7, blocking the degradation of cyclin E and c-Jun." (PMID 34203203, 2021). "Precious studies have found that STYX can act as an oncogene in colorectal cancer." (PMID 32884447, 2020).
cervical cancer (2 papers, 2022 to 2025). A primary or metastatic malignant neoplasm involving the cervix. "Members of the SNHG family regulate radiosensitivity through the ceRNA mechanism; SNHG6 sponges miR-485-3p, releasing STYX protein and thereby enhancing cervical cancer cell resistance to radiotherapy." (PMID 41301542, 2025). "Studies have shown that SNHG6/miR-485-3p/STYX axis contributes to the growth and radiation resistance of cervical cancer cells, thus promoting the progression of cervical cancer." (PMID 35692795, 2022). "Downregulation of SNHG6 or overexpression of miR-485-3p can reduce the expression level of STYX, while knockdown of miR-485-3p or overexpression of STYX can eliminate the effect of SNHG6 silencing on the growth of cervical cancer cells." (PMID 35692795, 2022).
endometrial cancer (2 papers, 2020 to 2022). Primary or metastatic malignant neoplasm involving the endometrium (mucous membrane that lines the endometrial cavity). "A lower FBXW7 expression and a higher expression of STYX were observed in human endometrial cancer tissues." (PMID 32239181, 2020). "Spearman’s correlation analysis further proved that the expression of FBXW7 correlated negatively with STYX in endometrial cancer tissues." (PMID 32239181, 2020). "The Western blot and qRT-PCR experiments validated that the expression level of STYX was up-regulated by pcDNA3.1-STYX and down-regulated by shSTYX in endometrial cancer cell." (PMID 32239181, 2020). "Generally speaking, all of our results demonstrated that STYX/FBXW7 axis participates in the development of endometrial cancer cell via Notch–mTOR signaling pathway." (PMID 32239181, 2020). "We also examined the expression level of FBXW7 and STYX in endometrial cancer cell lines." (PMID 32239181, 2020).
viral infection (1 paper, 2021). "Other low-TE genes include FAXDC2, STYX, and SHOC2 which are involved in the Ras/Raf/Mitogen-activated protein kinase/ERK Kinase (MEK)/Extracellular-signal-Regulated Kinase (ERK) cascade, commonly involved in viral infection, including that of coronaviruses." (PMID 34127534, 2021).
cancer (3 papers, 2020 to 2022). A tumor composed of atypical neoplastic, often pleomorphic cells that invade other tissues. "In addition, MK-STYX and STYX have been associated with oncogenesis, which further demonstrates the potential of targeting pseudophosphatases for cancer therapeutics." (PMID 35264672, 2022). "And therefore, STYX being active in several cancers, its role in modulating the NOTCH‐mTOR interaction through FBXW7 warrants further attention." (PMID 33822486, 2021). "However, some of the members participate in the promotion of cancer development, such as STYX, SSH1, and SSH3." (PMID 33053837, 2020). "STYX has a diffused expression in various tissues but not much is known about its biological role in cancers." (PMID 33822486, 2021).
tumor (2 papers, 2018 to 2025). "Apart from SAR1B, ZBTB33, STYX, KLRC3, and S100Z, there were significant differences in the other 10 DEGs levels in the tumor-stroma crosstalk." (PMID 30519576, 2018).
STYX also shares sentences with these, for which no sentence is quoted: diffuse large B-cell lymphoma (1 paper); infection (1); lymphoma (1).